INS (insulin)
Diseases named in the same sentence as INS in open-access papers (continued):
Sharing a sentence is not in itself a finding about the gene and the disease.
diabetes (continued). "Such classes of lipid and amino acid metabolites have been associated with improved insulin sensitivity in type 2 diabetes mellitus and altered lipid and amino acid metabolites following higher fibre and lower glycaemic foods in people with obesity." (PMID 39800861, 2025). "Diabetes, a metabolic disorder primarily attributed to a poor lifestyle, is caused by insufficient insulin secretion and/or impaired insulin utilization." (PMID 40219013, 2025). "Individuals with diabetes and obesity show higher rates of depression, anxiety, cognitive decline, and dementia, many of which are linked to impaired insulin signaling in the brain." (PMID 40539508, 2025). "Participants who achieved remission had a markedly lower hazard of initiating insulin, emphasising the clinical importance of weight loss in reducing treatment burden and potentially modifying the natural history of diabetes." (PMID 40119903, 2025). "Despite the presence of anti-insulin B cell populations in peripheral organs, T cell loss of Bcl6 in VH125SDBcl6ΔCD4 mice led to nearly complete diabetes protection relative to control VH125SD.NOD mice." (PMID 40909612, 2025). "Although the mechanisms are not clearly understood, short sleep duration can alter insulin signaling in adipocytes, leading to insulin resistance, which can increase the risk of diabetes." (PMID 41305794, 2025). "Further analyses revealed that the associations of both SCFAs and BCFAs with diabetes risk were attenuated after adjustment for baseline insulin measurements, including FI, HOMA-IR, and HOMA-B in overall population." (PMID 40078932, 2025). "As individuals age, insulin sensitivity decreases, and pancreatic beta-cell function declines, increasing the risk of type 2 diabetes mellitus." (PMID 40989682, 2025). "Over the decades, PT has evolved to a highly efficient treatment and remains the only causal diabetes therapy to reliably achieve total insulin independence." (PMID 41191602, 2025). "Polymorphisms in AGT have been associated with metabolic syndrome, type 2 diabetes mellitus (T2D), hypertension, and altered insulin sensitivity." (PMID 41300761, 2025). "While many clinical trials report short-term improvements in oxidative markers and insulin sensitivity, data on long-term outcomes, such as diabetes remission, cardiovascular risk reduction, or complication prevention, remain scarce." (PMID 40563357, 2025). "Diabetes, a chronic metabolic disease caused by insufficient insulin secretion or insulin resistance, characterized primarily by high blood sugar levels." (PMID 40260393, 2025). "Although insulin pump therapy is linked to lower risk of severe hypoglycemia, the impact of new diabetes device technology on FoH is less clear." (PMID 41212850, 2025). "The diabetes phenotype of patients with the INS variant was similar to that of patients with type 1 diabetes." (PMID 40303944, 2025). "One case–control study found normalization of endogenous glucose production, improved insulin sensitivity, and remission of diabetes in 16/24 patients with pre‐existing diabetes 2 years post‐liver transplantation for HCC‐associated cirrhosis." (PMID 40664615, 2025). "The American Diabetes Association has stated that exercise and weight loss can lower blood glucose by increasing insulin sensitivity and helping muscles to use glucose for energy, with or without insulin, and can also lower HbA1c over time." (PMID 41154998, 2025). "The effects of diabetes on the testicles are associated with mechanisms such as vascular damage, oxidative stress, insulin resistance, glucose toxicity, accumulation of glycation end products, inflammation, and apoptosis." (PMID 41280745, 2025). "In the STZ-diabetes model, combined multikinase inhibition alongside insulin administration was associated with suppression of HIF1α and VEGF in the retina and preservation of retinal architecture compared with diabetic controls." (PMID 41169477, 2025).
diabetes (continued). "Insights into these processes have emerged from studies of monogenic diabetes caused by INS gene mutations." (PMID 40392602, 2025). "GDM is characterized by increased insulin resistance and decreased insulin secretion and is associated with increased risk of the metabolic syndrome (MetS) and future diabetes." (PMID 41276872, 2025). "Type 1 diabetes mellitus is an autoimmune disease, primarily affecting children, characterized by the destruction of pancreatic β-cells responsible for insulin production, resulting in insulin deficiency and subsequent hyperglycemia." (PMID 41026724, 2025). "The results of the current study indicated that nurses in PHC facilities demonstrated good knowledge, except for the symptoms of ketoacidosis (62.3%), duration of intermediate-acting insulin (72.6%), and causes of hyperglycemia (73.5%)." (PMID 41573793, 2025). "Pancreatic dysfunction in diabetes involves β-cell loss and impaired insulin secretion, contributing to chronic hyperglycemia." (PMID 41208460, 2025). "The impact of these mechanisms is highlighted in monogenic conditions like Mutant INS-gene induced Diabetes of Youth (MIDY), where specific mutations in proinsulin greatly enhance its tendency to form insoluble aggregates." (PMID 41409210, 2025). "In STZ-induced diabetic rats, central activation of BAT thermogenesis is impaired and cannot be restored by peripheral insulin administration, suggesting central insulin resistance as a key factor underlying cold intolerance in diabetes." (PMID 40658727, 2025). "While there is often overlap in weight management and type 2 diabetes care, there are also unique challenges associated with type 2 diabetes (e.g., insulin management, diabetes stigma) that require specific intervention strategies." (PMID 40589510, 2025). "Of note, our subgroup analysis of patients using insulin, who typically have more advanced diabetes and higher mortality risk, showed a significant survival benefit in those also taking DPP-4 inhibitors." (PMID 40869643, 2025). "Type 2 diabetes, the dominant form of diabetes, is due to the progressive loss of pancreatic β-cell insulin secretion and is characterized by insulin resistance and metabolic dysfunction." (PMID 40831756, 2025). "The aim of our study is to evaluate the risk of diabetes-specific eating disorders in children with T1DM using continuous subcutaneous insulin infusion (CSII), with real-time glycemic data from continuous glucose monitoring (CGM)." (PMID 41010976, 2025). "Individuals with PHP1A are at increased risk of decreased insulin sensitivity, hyperglycemia, and diabetes, and understanding the underpinnings of their obesity is critical to help prevent and manage these metabolic complications." (PMID 40806967, 2025). "Our study results proved that it is possible to heal the injured pancreas in the STZ-induced diabetes in SD rats and cause the regeneration of insulin producing β-cells with FB treatment." (PMID 40723801, 2025). "Animal models of diabetes, including rodents with streptozotocin-induced diabetes or a genetic predisposition to diabetes, have been used to evaluate the effects of zeaxanthin on glucose metabolism and insulin sensitivity." (PMID 40143179, 2025). "As shown in animal models of diabetes, the loss of β-cell identity (dedifferentiation into immature phenotypes and transdifferentiation into other islet cell types) resulted in decreased insulin staining in islets of diabetic animals." (PMID 39860066, 2025). "The pathophysiology of diabetes-associated cognitive dysfunction is multifaceted, involving direct effects of chronic hyperglycemia, insulin dysregulation, vascular pathologies, and potentially other mechanisms." (PMID 39822993, 2025). "A randomized controlled trial study showed that an Asian dietary pattern improved insulin sensitivity and glucose metabolism, and induced weight loss and diabetes control." (PMID 40777173, 2025).
diabetes (continued). "These properties contribute to their potential role in supporting cardiovascular and metabolic health, improving lipid metabolism, enhancing insulin sensitivity, and lowering risk factors associated with conditions such as diabetes and metabolic syndrome." (PMID 41002973, 2025). "This method is designed to recover insulin production in patients with diabetes by transforming the hormone-secreting alpha cells, which are typically associated with glucagon production, into insulin-producing beta cells." (PMID 40913218, 2025). "Diabetes mellitus is a metabolic disorder that causes hyperglycemia due to insufficient insulin action." (PMID 40650275, 2025). "The progression of diabetes is closely linked to oxidative stress, chronic inflammation, and dysregulated insulin signaling, which collectively impair glucose metabolism and contribute to insulin resistance." (PMID 40429763, 2025). "The pathogenesis of diabetes is closely linked to impaired insulin secretion, with both T1D and T2D involving disruptions in insulin signaling." (PMID 40244147, 2025). "In diabetes mellitus, disrupted insulin signaling has been associated with increased Aβ accumulation in the brain." (PMID 40964391, 2025). "Our study reinforced the association between the TyG index and biochemical markers commonly associated with diabetes, such as HbA1c, fasting insulin, HOMA-IR, eGFR, WBC, hs-CRP, IL-6, and liver function markers, which is consistent with previous studies." (PMID 40065340, 2025). "Often misdiagnosed as other types of diabetes, such as type 1 or type 2 diabetes mellitus, type 3c diabetes mellitus is characterized by significant glucose variability, increased insulin requirements, and risk of hypoglycemia." (PMID 40401174, 2025). "Diabetes mellitus is one of the best‐known systemic diseases associated with periodontal disease caused by impaired insulin secretion, resistance to insulin action, or both." (PMID 40029768, 2025). "Elevated triglycerides appear to be a more proximal driver of diabetes risk, mediating much of hyperuricemia’s effect through hepatic lipid overflow and insulin resistance." (PMID 41019336, 2025). "Being able to self‐manage insulin in hospital when appropriate and safe is also recommended by international diabetes associations." (PMID 41358572, 2025). "Type 1 diabetes mellitus (T1DM) is an autoimmune disease caused by the destruction of insulin-producing pancreatic β-cells by autoreactive T cells." (PMID 41373714, 2025). "Nicotine affects body composition, insulin sensitivity and pancreatic β-cell function, thereby increasing the risk of diabetes." (PMID 40951432, 2025). "Type 1 diabetes mellitus is a multifactorial autoimmune disease characterized by the selective loss of pancreatic β cells, resulting in insufficient insulin production and chronic hyperglycemia." (PMID 40339569, 2025). "Patients 1 (with an HNF1A gene mutation, MODY3) and 5 (with an-INS gene mutation, MODY10) were initially diagnosed with type 1 diabetes mellitus (T1D) due to the immediate requirement for insulin therapy at diagnosis." (PMID 41020216, 2025). "cRegulon facilitated the delineation of the combinatorial regulatory network of HNF TFs, revealing their common TGs tightly associated with diabetes and insulin transport." (PMID 40707940, 2025). "Knowledge and practice were significantly associated with diabetes duration, insulin therapy length, and age, whereas the type of delivery device showed no significant impact." (PMID 41306599, 2025). "Abnormalities in vagal tone, balance, or sensitivity can impair insulin secretion, disrupt glucose homeostasis, and exacerbate metabolic dysfunctions associated with diabetes." (PMID 40305215, 2025). "The importance of tight glycaemic control was underscored by the landmark 1993 ‘Diabetes Control and Complications Trial’, which demonstrated that intensive insulin therapy significantly reduced the risk of long-term microvascular complications." (PMID 40718205, 2025).
diabetes (continued). "Logistic regression analysis of this study showed that age, high glycosylated hemoglobin, retinopathy with diabetes, hyperlipidemia, and blood glucose treatment (insulin injection group) were independent risk factors for high-risk foot of elderly diabetes." (PMID 40131908, 2025). "Diabetes mellitus is a chronic metabolic disorder characterized by persistent hyperglycemia caused by insufficient insulin production, the inability of the body to effectively utilize insulin, or a combination of both." (PMID 39815320, 2025). "Diabetes is primarily characterized by hyperglycemia, resulting from an absolute or relative deficiency in insulin activity, and is associated with systemic micro- and macro-vascular complications." (PMID 40666490, 2025). "Regular exercise can effectively reduce body fat and enhance insulin responsiveness, allowing cells to use insulin more efficiently to absorb glucose, thus lowering the risk of diabetes." (PMID 41040857, 2025). "Monogenic diabetes, though rare, has been identified in various forms, each with distinct genetic mutations affecting insulin secretion and action, with notable examples including GCK, HNF1A, HNF4A, HNF1B, and PDX1." (PMID 40862129, 2025). "Diabetes mellitus (DM) is a long-lasting metabolic disease characterized by persistent hyperglycemia caused by a defect in either insulin secretion by the pancreas or uptake of insulin, or both." (PMID 40776998, 2025). "IDE’s main substrate, insulin, is a peptide hormone regulating glucose homeostasis, and the loss of proper insulin signaling causes diabetes." (PMID 41463353, 2025). "The eGDR is a marker of insulin sensitivity, strongly linked to metabolic syndrome, diabetes, and related complications." (PMID 40421241, 2025). "Both types of diabetes are linked by the need for insulin therapy, but the administration of insulin has its own set of challenges, prompting ongoing research into improved delivery methods." (PMID 40352348, 2025). "In this section, we summarize key microproteins implicated in glucose and insulin regulation and discuss their potential translational applications in diabetes management." (PMID 41465308, 2025). "The objective of this retrospective cohort study is to assess the association between insulin use and glycemic control, as measured by changes in hemoglobin A1c (A1c) levels, among patients with type 2 diabetes mellitus during the COVID-19 pandemic." (PMID 40700264, 2025). "Many studies have reported a link between artificial sweetener intake and an increased risk of type 2 diabetes mellitus, potentially driven by changes in gut microbiota composition, higher glucose absorption, and insulin insensitivity." (PMID 40443994, 2025). "In contrast, we showed that booster shots of the COVID‐19 vaccine altered insulin sensitivity and increased the risk of diabetic complications in patients with diabetes, as measured using biological indices of insulin sensitivity." (PMID 41190280, 2025). "This addresses a core aspect of the management of diabetes, enhancing sensitivity to insulin and lowering the risk of cardiovascular damage." (PMID 40116715, 2025). "In general, for postpartum women, engaging in regular exercise can help control weight, improve insulin sensitivity and reduce blood sugar levels, thereby reducing the risk of diabetes." (PMID 41523956, 2025). "The hallmark of diabetes mellitus, a chronic metabolic disease, is persistent hyperglycemia brought on by compromised insulin secretion, insulin action, or both." (PMID 40751071, 2025). "Background/Objectives: Diabetic ketoacidosis (DKA) is a common acute complication of diabetes with treatment consisting of reversal of cause, insulin administration, fluid resuscitation and electrolyte repletion." (PMID 40407548, 2025).
diabetes (continued). "According to a Position Statement of the American Diabetes Association, glycemic responses to exercise are highly variable and depend on factors such as activity type, timing, intensity, and circulating insulin levels." (PMID 40217942, 2025). "Diabetes is a chronic and metabolic disease characterised by raised blood sugar concentration (hyperglycaemia) caused either by deficient insulin production (type I diabetes) or by insulin resistance (type II diabetes)." (PMID 40801339, 2025). "Our data suggest that patients with longer diabetes duration and those undergoing treatment with insulin, metformin, or PPIs are at higher risk of developing hypomagnesemia." (PMID 40647173, 2025). "Many patients often require intensified therapy, including early insulin initiation, recommended by consensus guidelines for the treatment of insulin deficiency in diabetes secondary to CP." (PMID 40401174, 2025). "Herein, we report that ginger extract ameliorated diabetes, which was reflected by preventing weight loss, lowering glycemia, and increasing serum insulin levels, possibly through the stimulation of β-cell neogenesis." (PMID 40014427, 2025). "Hypoglycemia is a common occurrence in patients with various forms of diabetes and is primarily caused by an imbalance between glucose supply and antidiabetic treatments, particularly insulin, sulfonylureas, and glinides." (PMID 40150028, 2025). "T2DM results from the progressive dysfunction of pancreatic β‐cells, alongside decreased sensitivity of peripheral tissues to insulin." (PMID 40823947, 2025). "Diabetes is a chronic disease caused by the pancreas’ insufficient ability to secrete insulin or the body’s failure to effectively utilize the secreted insulin, affecting more than 537 million people worldwide." (PMID 39852068, 2025). "Dorea is associated with insulin production and fasting blood glucose levels, potentially contributing to type 2 diabetes mellitus and weight gain." (PMID 40650144, 2025). "Diabetes in MIDD is believed to be caused by a gradual decrease in insulin production due to reduced manufacturing of ATP by the pancreatic cells with mutated mitochondria and by increased oxidative stress from reactive oxygen species." (PMID 40471292, 2025). "High-risk groups (e.g., insulin-treated diabetes, HeFH, and ACS) benefited the most, with some studies reporting notable MACE reductions." (PMID 40110272, 2025). "The role of insulin and insulin resistance that leads to diabetes and cardiovascular risk is well known even in childhood." (PMID 40153416, 2025). "Vitamin D deficiency has been specifically associated with reduced insulin secretion, insulin resistance, and the development of type 2 diabetes mellitus." (PMID 39935579, 2025). "Insulin is a hormone secreted by beta cells in the pancreas, responsible for transferring blood glucose into cells for energy use." (PMID 40417223, 2025). "This case highlights that EIAS, an under-recognized cause of unpredictable glycemia in insulin-treated diabetes, should be considered in patients with severe hypoglycemia and high insulin requirements." (PMID 41696731, 2025). "Diabetes is characterized as an increased blood glucose level that is caused by either a defect in insulin action, insulin secretion, or both, causing various metabolic disorders." (PMID 40357213, 2025). "Type 2 diabetes mellitus (T2DM) is characterized by progressive loss of insulin secretion from pancreatic islet β-cells due to IR (insulin resistance), which is a feature of metabolic syndrome (MetS)." (PMID 41614828, 2025). "The association between VDD and diabetes is based on the postulation that vitamin D can improve the body’s sensitivity to insulin, the hormone responsible for regulating blood sugar levels, and thus reduce the risk of diabetes." (PMID 39312091, 2025). "CaMKII is activated in diabetes, significantly contributes to the risk of cardiac arrhythmias, and has been involved in insulin secretion alteration." (PMID 40287491, 2025).